CD4 (CD4 molecule)
Diseases named in the same sentence as CD4 in open-access papers (continued):
Sharing a sentence is not in itself a finding about the gene and the disease.
tumor (continued). "On average, metastatic samples were undergoing heavy immunomodulation compared to a quieter immunomodulatory environment of the primary tumour and normal tissue despite showing less immune cell infiltration of CD4 + T cells, CD8 + T cells, and plasma cells." (PMID 35904677, 2022). "To get more convincing evidence, after patients informed consent, we collected 8 PCP tumor samples for immune historical staining and 5 biomarkers of immune infiltration cells were detected including CD4, CD8, CD20, CD56, and CD163." (PMID 36389809, 2022). "In terms of direct anti-tumor immune responses, little is known about CD4+ T cells, though recent studies have demonstrated that CD4+ T cells also produce granzymes and perforins with cytotoxic activity as an anti-tumor effect." (PMID 36611881, 2022). "By secreting different tumoricidal cytokines, such as interferon-γ (IFNγ) and TNFα, CD4+ T cells, also named CD4+ helper (Thelpers), support CTLs in the disruption of primary tumor cells." (PMID 35267528, 2022). "The generation of tumor-specific T cell responses occurs via costimulatory signals that allow for the generation and expansion of activated tumor-specific CD4+ and CD8+ T-cells." (PMID 35632496, 2022). "The coexpression of CD161 with OX40 and lack of expression of 4-1BB also suggests that they can both play a critical role in the establishment of a robust CD4 memory pool of tumor-specific T cells that can vigorously respond upon rechallenge." (PMID 35185935, 2022). "Conversely, CD4+ T-helper 2 and FoxP3+ regulatory T cells seem to contribute to tumor immune escape." (PMID 36010653, 2022). "CD8+ T lymphocytes attack tumor cells via cytotoxicity, while CD4+ T lymphocytes exhibit potent anti-tumor immune response." (PMID 36483600, 2022). "Interestingly, women >55 years had increased CD4+ in tumor tissue compared to younger women, suggesting that lower estrogen and progesterone levels may be associated with increased CD4+ T cell infiltration into the TME, similar to what has been observed in NSCLC." (PMID 36387163, 2022). "A greater understanding of the biology of tumor-reactive CD4+ Th cells would help define their role in the antitumor immune response." (PMID 35439168, 2022). "Tumor-infiltrating CD4+ and CD8+ lymphocytes persisted for a long time (>50 months), as observed in resected regrown tumors and at autopsies." (PMID 35864254, 2022). "The percentage of CD4+CD25+ Tregs in the spleen was significantly higher in the B16-tmCRT/39-272 tumor-bearing mice than in the B16-EGFP controls (16.88% vs 20.9%), which contributed to enhanced the tumorigenesis of B16-tmCRT/39-272." (PMID 36249426, 2022). "Upon tumor antigen stimulation, naïve T cells are activated and differentiate into two broad classes of CD4+ or CD8+ T cells that have distinct effector mechanisms." (PMID 35966597, 2022). "Systemic JX-594 delivery remodeled the primary TME and lung metastatic sites by increasing tumor-infiltrating CD4/8+ T cells and dendritic cells." (PMID 35052851, 2022). "Current understanding is that CD8+ T cells, CD4+ Th1 cells, NK cells, B cells, classically activated macrophages (M1) and mature dendritic cells are hostile to tumours and participate in tumour control and elimination." (PMID 36180554, 2022). "Although CD8+ T cells were killed by exosomal pGSN, naïve CD4 T cells were preferentially polarized into type 2 helper T cells (Th2); responses that contribute to tumor growth and chemoresistance." (PMID 36291171, 2022). "As an integral component of the anti-tumor immunity, peripheral blood CD4+ T cells help regulate and promote priming, migratory potential, and killing activity of cytotoxic T lymphocytes (CTLs)." (PMID 35484541, 2022). "Demographic and clinical data [age, sex, HIV status, antiretroviral therapy (ART) history, CD4 count, plasma viral load] and tumor biopsies were collected from 243 consenting patients." (PMID 35494029, 2022).
tumor (continued). "Our data support previous findings, demonstrating both CD8+ and CD4+ positive T cells in tumour stroma of stage IV CRC." (PMID 36612217, 2022). "The percentage of CD4-C1-CD69 (CD4+ activated T cells) among CD4+ T cells isolated from tumor tissues and paracancer tissues was much higher than other cell types, indicating the potential enrichment of CD4+ activated T cells in the TME." (PMID 36466840, 2022). "Tumor regression was dependent on class II-restricted recognition of tumors by tumor-reactive CD4+ CTLs which developed cytotoxic activity and kill tumor." (PMID 36311701, 2022). "Depletion of intestinal microbiota inhibited the activation of DCs, CD4+ T cells and cytotoxic NK cells in tumor tissues upon trastuzumab treatment via an IL12p70-dependent mechanism." (PMID 36726985, 2022). "Immunization with CD4+ TLEX-CD8086 cells significantly inhibited tumor growth compared with that in mice immunized CD4+ TLEX-null cells and LEX-CD8086." (PMID 36466863, 2022). "For example, As an indispensable component for mediating immune homeostasis, Tregs play essential roles in tumor immunity by inhibiting the activation and differentiation of CD4+ helper T cells and CD8+ cytotoxic T cells." (PMID 35493077, 2022). "In parallel, while CD4+ T- and B-cell fractions decreased upon tumor progression, their respective PD-1+ portions also increased significantly." (PMID 35493461, 2022). "The first is a rare, aggressive, and well-documented neoplasm, initially described as CD4+ CD56+ neoplasm, with frequent skin involvement and leukemic dissemination, mainly affecting elderly men." (PMID 36077669, 2022). "Although CD8+ T cells are known to play a pivotal role in antitumor immunity, CD4+ T cells also contribute to direct tumor killing besides their supporting role as cytokine producers." (PMID 36311701, 2022). "Recent studies have shown that subpopulations of neoantigen-reactive CD8+ and CD4+ tumor infiltrating lymphocytes (TILs) have a Trm phenotype and are highly prognostic for patients with HNSCC and other cancer types." (PMID 36106641, 2022). "CD4 + cells can differentiate into subtypes that both serves as anti-tumor effectors (Th1 lineage) or suppressor cells (CD4 + CD25 +)." (PMID 35172762, 2022). "Alternatively, CD4+ T cells can directly exert anti-tumor responses by recruiting NK cells and macrophages through IFN-γ or direct cytolytic effects." (PMID 36230990, 2022). "In another case of a patient with metastatic cholangiocarcinoma, CD4+ T cells in the tumor-infiltrating lymphocyte (TIL) population exhibited cytotoxic potential in vitro." (PMID 36159781, 2022). "On a functional level, in vivo studies in colitis-associated cancer were able to confirm that TGFβ relevantly contributed to the intratumoral accumulation of IL-17A+ IL-22+ CD4+ T cells and thereby obviously triggered IL-22-dependent tumor-promoting effects." (PMID 36428508, 2022). "LAG-3 is expressed on activated tumor-infiltrating lymphocytes (TILs) (for example CD4 and CD8 positive T-cells, T-regs and B-lymphocytes), and it regulates T-cell function as an inhibitory ICP." (PMID 36289918, 2022). "By contrast, tumor-bearing WT and KO mice had similar percentages of Ki-67+ tumor-infiltrating CD4+ T cells." (PMID 35143421, 2022). "Although they express MHC class II molecules, little is known about their ability to present tumor antigens to tumor-infiltrating CD4 T cells, and the consequences of such presentation." (PMID 35903540, 2022). "As TGF-β is required for CD103 induction, this finding is highly consistent with a previous publication showing that CD4 T cell-produced cytokine TGF-β1 suppresses anti-tumor immunity." (PMID 36229613, 2022). "Overall, these findings support the possible biological implication of our results showing increased Ki-67 and granzyme B expression by tumor infiltrating CD4+ and CD8+ T cells in mice treated with a combination of AHCC® and DICB therapy." (PMID 35514996, 2022).
tumor (continued). "By injecting a tumor vaccine, CD4+ and CD8+ effector T cells can be induced to clear tumor cells in the patient and enable host cells to avoid attack." (PMID 36124030, 2022). "Here, we developed a score based on quantification of two TIL subsets: T helper and T reg (CD4 and FoxP3) lymphocyte subpopulations, significantly different in intraepithelial tumor component when compared to NOM." (PMID 34626165, 2022). "Specifically, T-cell CD4 memory activated and macrophages M1 were enriched in normal tissues, whereas Tregs were increased in tumor tissues." (PMID 35875096, 2022). "In another approach, when TGFBR2 is depleted in CD4+ T cells, a remodeling of the vasculature in the tumor leads to the death of tumoral avascular regions and suppresses the tumor progression." (PMID 35565420, 2022). "We performed sub-clustering analysis to determine the type of T cells present and found that the population of CD8 + T central memory (Tcm) cells decreased and that of CD4 + Tcm cells increased in tumor tissue." (PMID 35087207, 2022). "Those tumours with loss of function in genes such as HLA-A, NLRC5 will lose the ability to present tumour neoantigens to dendritic cells or CD4 T cells." (PMID 36531162, 2022). "CD44-HBEGF and ANXA1-FRR1, both related to tumor progression, were also exclusive L–R pairs programming CD4, CD8, DC, Gran, and Mφ interactions." (PMID 36008393, 2022). "Tumor vaccines also boost CD4 + T cell-derived secretion of TH1-characteristic tumoricidal cytokines (e.g., IFNγ), which have direct anti-tumor activity." (PMID 36316782, 2022). "Although some studies have shown that IFN-γ inhibits the immunosuppressive function of tumor-induced MDSCs, cryo-thermal CD4+ T cells regulating the maturation of MDSCs should be addressed." (PMID 35874660, 2022). "Here the authors show that tumor-expressed B7x promotes the conversion of conventional CD4+ T cells into regulatory T cells within the tumor microenvironment to promote immune evasion and resistance to anti-CTLA-4 therapy." (PMID 35523809, 2022). "Meanwhile, the deletion of c-MYC at the CD4+CD8+ stage of T cell development prevents tumour formation induced by NOTCH1." (PMID 35681778, 2022). "The treatment resulted in the proliferation of both CD4+ and CD8+ T cells, being suggestive of DC fused cells’ ability to produce a variety of tumor-associated antigens that can be recognized by the immune system." (PMID 35214655, 2022). "Calcipotriol treatment markedly suppressed PyMtOvatg TslprKO tumor growth in TslprKO mice that received WT CD4+ T cells (P = 0.0029)." (PMID 35657353, 2022). "We first depleted either CD4 +or CD8+T cells in TC-1 tumor-bearing mice (n=5) by injecting them with either 200 μg of anti-mouse CD4 antibodies or 100 μg of anti-mouse CD8 antibodies daily for 3 days, followed by Alb-IFNβ and E7 vaccination." (PMID 35459734, 2022). "M1 macrophages which have anti-tumor effects can kill tumor cells and present tumor antigens to CD4+ T cells." (PMID 35136176, 2022). "Various theories have been proposed describing the involvement of naïve and memory CD4 + T cells in tumor immunity." (PMID 35858901, 2022). "Similar to their frequency in the peripheral blood, CD4 T cells account for a large portion of the T cells in the tumor." (PMID 35937775, 2022). "CIBERSORT results showed that the MRG-low subgroup had a higher abundance of tumor-promoting immune cells, including monocytes and resting mast cells, and other immune cells, such as resting CD4+ T memory cells and resting DCs." (PMID 36293001, 2022). "Studies have shown that the combination of LAG-3 and MHC-II contributes to avoiding apoptosis of tumour cells and promoting tumour-specific CD4+ T-cell recruitment but reduces the response of CD8+ T cells." (PMID 35494015, 2022).
tumor (continued). "We found that myeloid cells from two clusters (aMΦ, bMΦ), characterized by the expression of tumor-associated macrophage genes (CD163, CCL4, APOE, and HLA-DRA) were strongly connected to the CD8+ exhausted and CD4+ Th1 T cell clusters." (PMID 35177622, 2022). "Combination therapy significantly reduced tumor infiltration of immunosuppressive CD4+/CD25+/FOXP3+ Tregs." (PMID 35392977, 2022). "In murine renal adenocarcinoma-bearing mice, the use of an anti-CCR5 increases the CD8 T cells (together with CD4 and DCs) within the tumor and retards the tumor progression." (PMID 36429101, 2022). "Among tumor-infiltrating Tregs, investigators detected T-bet+Foxp3+CD4+ T cells with a higher expression of typical Treg factors, such as ICOS, GITR, CD103, CTLA4, PD-1, and IL-10 as compared to CD4+ T cells, which express either T-bet or Foxp3." (PMID 35626725, 2022). "In conclusion, the antitumor activity of CD24+MDSC-DCs was achieved by inhibiting the polarization of CD4+T cells toward Tregs, therefore reducing the proportion of Treg in tumor and changing the immunosuppression of TME." (PMID 35707772, 2022). "Further exploration in the tumor microenvironment confirmed the enrichment of CD8+ T cells, CD4+ T cells and natural killer cells in PCSK9‐deficient tumors." (PMID 34962050, 2022). "We next set up to identify the class II+ cell at the tumor site responsible for tumor antigen presentation to CD4 T cells." (PMID 35903540, 2022). "On the other hand, TEXs can also indirectly transfer tumor antigen to antigen presenting cells, like DCs, and then activate the cytotoxic activity of CD8+ T cells and CD4+ T helper cells, so as to inhibit tumor growth." (PMID 35582534, 2022). "In this study, it was found that the content of T cell CD4 memory activated in tumor tissue was significantly increased." (PMID 35422890, 2022). "We used TIMER online tool to explore association between hub genes and six immune cell types (CD4+/CD8+ T cells, B cells, macrophages, neutrophils and dendritic cells) and tumor purity by the Spearman tests." (PMID 35452485, 2022). "Patients with longer survival had a distinct CD4 helper T cell infiltrate in the tumor tissue lower immunosuppressive tumor gene expression signatures and frequencies of immune cell types associated with immune suppression." (PMID 35662283, 2022). "Several studies demonstrated the antigen presentation of B cells plays a critical role in tumor-specific CD4+ and CD8+ T cell activation." (PMID 36033455, 2022). "Unexpectedly, the NA2 cells led to CD4 + CD8+ tumor formation in one of the mice, which probably arose from the few double positive cells present at the time of injection." (PMID 35246138, 2022). "We found that we did achieve more statistical significance, for example CTLA-4 and ICOS were significantly decreased on the surface of tumour-infiltrating CD4+ T cells compared with the treatment-naïve setting." (PMID 35366537, 2022). "CD4+ T cells participate in anti-tumor immunity and prevent immune escape by regulating the immune response." (PMID 35719927, 2022). "This strategy led to a significant reduction in lymphoma growth, an increase in the number of tumor-infiltrating CD4+ and CD8+ T cells, and the promotion of EBV-specific T-cell responses." (PMID 35559250, 2022). "Mouse subcutaneous tumors with ACYP1 overexpression exhibited significantly accelerated tumor progression with increased aggregation of CD4+ T cells." (PMID 35586489, 2022). "Conversely, Type 2 CD4 T-helper cells (Th2), such as Tregs (FOXP3 + CD4 regulatory T-cells) functionally reduce the number of CTL to enhance tumor growth, resulting in an immunosuppressive microenvironment." (PMID 36145510, 2022). "Meanwhile, RAB6B expression was related to the infiltrating abundance of various tumor-associated immune cells in HCC, including B cells, CD8+ T cells, CD4+ T cells, macrophages, neutrophils, and DCs." (PMID 36120364, 2022).
tumor (continued). "The PCa tumor immune microenvironment (TME) is characterized by the limited presence of tumor-infiltrating lymphocytes (TILs), represented mainly by CD4+ regulatory T cells with a restricted number of CD8+ cells." (PMID 35955671, 2022). "Interest in the CD4 response as a major player of immunotherapy efficacy was redoubled as the involvement of tumor-Ag-specific CD4 T cells at the tumor site in response to ICB began to be unveiled." (PMID 35954341, 2022). "On the contrary, a significant increase in NK-T cells and type I NK cells (CD56 pos/CD4 pos) occur in the tumor tissues." (PMID 36010863, 2022). "The GR group compared to the BR group had significant enrichment in CD3+ (stroma—p < 0.001, tumor—p < 0.001), CD8+ (stroma—p = 0.001, tumor—p < 0.001), CD4+ (stroma—p = 0.009, tumor—p = 0.004), and CD45R0+ (tumor—p = 0.014) cells." (PMID 35455743, 2022). "We discovered that simultaneous inhibition of the histone methyltransferases G9A and EZH2 activates the CXCL10–CXCR3 axis and increases homing of intratumoral effector lymphocytes and natural killer cells while suppressing tumor-promoting FoxP3+ CD4 T cells." (PMID 35131874, 2022). "The phenotypes of NK cells, CD8+ T cells, DCs, macrophages and MDSCs in CD4- splenocytes were further analyzed after coculturing with CD4+ T cells from the tumor-bearing or cryo-thermal treated mice, and comparisons made." (PMID 35874660, 2022). "Mice treated with AHCC® and DICB had increased expression of Ki-67 and decreased expression of PD-1 by tumor infiltrating CD4+ T cells compared to mice treated with water and DICB." (PMID 35514996, 2022). "There was a higher proportion of HLADR-expressing macrophages (M1) and CD4 Th cells in indolent tumours and conversely a higher M2:M1 ratio in aggressive tumours." (PMID 35975974, 2022). "Addition of CXB to ICB and CTX was accompanied by diminished accumulation of intratumoral neutrophils and monocytes, and an increase in the fraction of tumor-infiltrating IFNγ-producing CD4+ and CD8+ T cells." (PMID 35440553, 2022). "The results indicated that NCBP2 expression was positively correlated with the immune infiltration levels of macrophages and CD4+ T cells across most tumor types, with the highest correlation shown in LIHC." (PMID 36010268, 2022). "Through IHC, we observed more tumor infiltration of CD4+ T and CD8+ T cells after rAAV infection compared with the PBS group." (PMID 35615262, 2022). "CD4+ T cells trigger continuous T cell initiation, expansion and antigen spread, thus expanding the anti-tumor T cell repertoire." (PMID 35303904, 2022). "In luminal subtype, NTN4 expression level was negatively associated with tumor purity (r = − 0.258, P = 9.80e−10), whereas positively associated with B cells, CD8+ T cells, CD4+ T cells, macrophages, neutrophils, and DC." (PMID 35732855, 2022). "We also highlight the critical role of CD4+ T cells during cancer therapies and discuss potential strategies harnessing CD4+ T cells to control tumor progression and improve outcomes in cancer immunotherapy." (PMID 35008422, 2022). "Other preclinical studies suggest synergy in IL-3 production and activated CD4+ T-cell tumor infiltration when combining DC vaccines with anti-CTLA-4 therapy." (PMID 36290818, 2022). "In the presence of autologous tumor cell membranes (TM), CD4+ and CD8+ T cells activated by FO or the crude lysates from FOLactis significantly had at least about a three-fold increase in surface expressions of CD69 and CD25 compared with the TM group." (PMID 36463242, 2022). "At the same time, the tumor stimulates the differentiation of Naive CD4 + T cells to produce more CD4 + Central Memory, which participates in the immune response of the tumor." (PMID 36507493, 2022). "It was showed that the anti-tumor efficacy of CD4 CAR T cells alone was better than that of CD8 CAR T cells alone or mixture of CD4 and CD8 CAR T cells, because CD8 CAR T cells were more prone to exhaustion under high tumor burden." (PMID 36568989, 2022).